PRR11 (proline rich 11)
Diseases named in the same sentence as PRR11 in open-access papers (continued):
Sharing a sentence is not in itself a finding about the gene and the disease.
cancer (continued). "With regard to its biological function, PRR11 could be initially prominent for its correlation with the cell cycle of cancer cells." (PMID 36551227, 2022). "Preliminary experiments found that SonoVue microbubbles-mediated RNA interference targeting PRR11 could exert anti-cancer effects, forecasting the potential application of PRR11 for targeted therapy." (PMID 36551227, 2022). "Therefore, PRR11 acts as a promising prognostic indicator in a limited number of human cancers, gradually manifesting its potential application for targeted therapies." (PMID 36551227, 2022). "Moreover, traumatic autophagy, instead of protective autophagy, is notably reduced by PRR11 in cancer cells." (PMID 36551227, 2022). "Then we showed that interfering PRR11 on three cancer cell lines could greatly inhibit cell proliferation and migration and arrest cells to S phase in vivo." (PMID 36060253, 2022). "In the present study, PRR11 was highly expressed in 19 out of 33 kinds of cancers in TCGA." (PMID 36060253, 2022). "This is similar to the results of previous studies of PRR11 in other malignant tumors." (PMID 34659555, 2021). "Moreover, the migration capability of the cancer cells determined was significantly reduced after knocking down the expression of PRR11." (PMID 33276775, 2020). "Of note, CDK4/6 inhibitors exhibited similar opposite connectivity, suggesting these agents may also be effective against PRR11-amplified cancers." (PMID 33127913, 2020). "Several candidate gene products (UCHL1, SNAT1, and EGR1) were selected to investigate whether PRR11 influences their expression in HC cancer cells." (PMID 25971332, 2015). "Moreover, expression of PRR11 in cancer cells in invasive and metastatic areas was much more intense than normal biliary epithelium and low grade IEN." (PMID 25971332, 2015). "Moreover, the novel role of PRR11 in modulating PTTG1 expression showing its positive function in the cell cycle will likely encourage people to study the functions of PRR11 in the development of pan-cancer." (PMID 36060253, 2022). "Notably, PRR11 may play an oncogenic role in pan-cancer progression by regulating the expression of PTTG1 to involve in the cell cycle." (PMID 36060253, 2022). "Therefore, exploring more miRNAs targeting PRR11 3′-UTR might be a reliable approach to regulate PRR11 expression in cancer treatment." (PMID 36551227, 2022). "In this review, we summarize functional activities, related signaling pathways and biological molecules of PRR11 in various malignancies and generalize potential application of PRR11 for targeted therapies, thereby contributing to further exploration of PRR11 in cancer treatment." (PMID 36551227, 2022). "Therefore, we found that PRR11 served as an oncogene in pan-cancer and could influence the cell cycle progression through regulating the expression of PTTG1 by interacting with the transcription factor E2F1." (PMID 36060253, 2022). "Notably, ultrasonic irradiation and SonoVue microbubbles-mediated RNA interference targeting PRR11 could exert anti-cancer effects via PRR11." (PMID 36551227, 2022). "PRR11 silencing could suppress the expression level of PTTG1 in pan-cancer." (PMID 36060253, 2022). "Therefore, PRR11 exerts oncogenic effects on several human cancers, which could be applied into clinical cancer treatment." (PMID 36551227, 2022). "It was found that PTTG1 involved in the cell cycle was upregulated in 10 out of 11 cancers and downregulated in NCI-H460 and BxPC3 cancer cell lines with interfering PRR11." (PMID 36060253, 2022). "Thus, PRR11 silencing in pan-cancers could suppress the expression level of PTTG1." (PMID 36060253, 2022). "Hence, PRR11 might be great of biological significance in tumorigenesis of human cancers." (PMID 36551227, 2022).
cancer (continued). "However, the precise molecular mechanisms underlying how PRR11 regulates the expression of genes involved in different signaling pathways and whether high-expressed PRR11 has a common regulatory mechanism in the development of different cancer types are yet to be elucidated." (PMID 36060253, 2022). "Intriguingly, it was found that the expression levels of both PRR11 and PTTG1 were extremely correlated to genes involved in the cell cycle across various cancer types." (PMID 36060253, 2022). "Recent studies reported that the gene pair of PRR11 and SKA2 is involved in tumorigenesis and cancer progression." (PMID 32565988, 2020). "In the cancer tissues analyzed, the staining observed for expression of both EGR1 and PRR11 protein nearly overlapped in the same regions, indicating a consistent expression pattern between these two markers." (PMID 33276775, 2020). "Furthermore, it was found that PRR11 regulates PDL1 via SPDL1, impacting immunotherapeutic efficacy in both cancers." (PMID 38760964, 2024). "In the current study, we found that PRR11 was upregulated in 19 cancer types compared with that of normal tissues and high-expressed PRR11 was a predictor of poor prognosis in 10 cancer types by bioinformatics." (PMID 36060253, 2022). "In addition, a GEO data set (GSE48075) verified that high expression of PRR11 and PTTG1 was significantly related to the poor prognosis of cancer patients." (PMID 36060253, 2022). "Here, several growth-associated genes were up-regulated, including RNA helicase (HELLS), PRR11, CDCA8, and DNA topoisomerase 2 (TOP2A), HMGB2, EIF2B4, and CDKN3, which are thought to serve important functions during growth stimulation, many of which are known to be up-regulated in various cancers." (PMID 37907238, 2024).
cancers of the digestive system (1 paper, 2015). "PRR11 expression was evaluated in 6 different cancers of the digestive system." (PMID 25971332, 2015).
gastrointestinal tumor (1 paper, 2015). "Although the current study sheds light on the pattern of PRR11 expression in six gastrointestinal tumors and potential clinical significance of PRR11 in HC, the potential functions and underlying mechanisms of PRR11 overexpression remain unclear." (PMID 25971332, 2015). "In the current study, immunohistochemical techniques were used to assess expression levels of PRR11 in six gastrointestinal tumor types and the expression of PRR11 was correlated with clinical outcomes in patients with HC." (PMID 25971332, 2015). "In summary, this study demonstrates that PRR11 is widely up-regulated in human gastrointestinal tumors, including HC." (PMID 25971332, 2015). "Expression of PRR11 was significantly altered in 5 tumors of digestive system (ESCC, GC, PDC, CRC, and HC), but not in HCC." (PMID 25971332, 2015).
infection (1 paper, 2015). The state of being infected such as from the introduction of a foreign agent such as serum, vaccine, antigenic substance or organism. "Infection with the PRR11-shRNA was accompanied by a decreased level of PRR11 mRNA and protein." (PMID 25971332, 2015).
PRR11 also shares sentences with these, for which no sentence is quoted: colorectal cancer (3 papers); sarcoma (2); squamous cell carcinoma (2); benign tumors (1); carcinoma of the tongue (1); cervical squamous cell carcinoma (1); colorectal tumors (1); endocervical adenocarcinoma (1); Ewing sarcoma (1); gastric tumors (1); mesothelioma (1); metabolic disease (1); pancreatic adenocarcinoma (1); pancreatic ductal carcinomas (1); pheochromocytoma (1); pheochromocytoma and paraganglioma (1); pleural mesothelioma (1); rectum adenocarcinoma (1); skin cutaneous melanoma (1); triple-negative breast carcinoma (1); uterine cancer (1).